RN7SL767P (RNA, 7SL, cytoplasmic 767, pseudogene)
Gene: Miscellaneous RNA gene on chromosome 3 (113,632,704 to 113,632,998, forward strand). Ensembl gene ENSG00000241529.
Homologues: Orthologues: chimpanzee Metazoa_SRP (72% identical). Paralogues in human: RN7SL396P (69% identical), RN7SL752P (67% identical), RN7SL1 (66% identical), RN7SL5P (65% identical), RN7SL674P (65% identical), RN7SL2 (65% identical), RN7SL3 (65% identical), RN7SL4P (64% identical), RN7SL128P (62% identical), RN7SL296P (61% identical), RN7SL357P (61% identical), RN7SL480P (61% identical), and 695 more.